HM13 (histocompatibility minor 13)
Description:
Catalyzes intramembrane proteolysis of signal peptides that have been removed from precursors of secretory and membrane proteins, resulting in the release of the fragment from the ER membrane into the cytoplasm. Required to generate lymphocyte cell surface (HLA-E) epitopes derived from MHC class I signal peptides. May be necessary for the removal of the signal peptide that remains attached to the hepatitis C virus core protein after the initial proteolytic processing of the polyprotein. Involved in the intramembrane cleavage of the integral membrane protein PSEN1. Cleaves the integral membrane protein XBP1 isoform 1 in a DERL1/RNF139-dependent manner. May play a role in graft rejection (By similarity).
Synonyms: IMPAS-1; H13; IMP1; PSL3; SPP; MSTP086; dJ324O17.1; IMPAS; PSENL3; SPPL1; HM13-IT1
Tractability: Antibody: UniProt places it where antibodies can reach, with medium confidence; UniProt predicts a signal peptide or a membrane-spanning region; its Gene Ontology location is reachable by antibodies, with medium confidence. PROTAC: ubiquitination databases record sites on it; its protein half-life has been measured.
Target class: Enzyme; Hydrolase
Gene: Protein-coding gene on chromosome 20 (31,514,370 to 31,577,923, forward strand). Ensembl gene ENSG00000101294.
Subcellular location: Endoplasmic reticulum membrane; Membrane; Cell membrane (Isoform 4)
Subcellular location (Human Protein Atlas): Endoplasmic reticulum
Pathways (Reactome):
Cellular responses to stimuli: Regulation of HMOX1 expression and activity
Gene Ontology:
Molecular function: aspartic endopeptidase activity, intramembrane cleaving; peptidase activity; protein binding; protein homodimerization activity; ubiquitin protein ligase binding
Biological process: membrane protein ectodomain proteolysis; membrane protein intracellular domain proteolysis; membrane protein proteolysis; retrograde protein transport, ER to cytosol; cellular response to oxidative stress
Cellular component: cytoplasmic side of endoplasmic reticulum membrane; Derlin-1 retrotranslocation complex; endoplasmic reticulum; endoplasmic reticulum membrane; lumenal side of endoplasmic reticulum membrane; membrane; rough endoplasmic reticulum; cell surface; plasma membrane
Genetic constraint (gnomAD): Loss-of-function variants: 15 observed, 40.94 expected, observed/expected ratio (o/e) 0.37, 90% interval 0.24 to 0.56. The upper end of that interval is the gene's LOEUF score, 0.56, which puts it in group 2 of 6, group 1 being the genes least tolerant of losing a copy. Missense variants: 388 observed, 533.57 expected, observed/expected ratio (o/e) 0.73, 90% interval 0.67 to 0.79. Synonymous variants: 191 observed, 220.63 expected, observed/expected ratio (o/e) 0.87, 90% interval 0.77 to 0.98.
Homologues: Orthologues: dog HM13 (98% identical), pig HM13 (97% identical), macaque HM13 (92% identical), guinea pig HM13 (90% identical), rat Mcts2 (89% identical), chimpanzee HM13 (85% identical), mouse H13 (85% identical), rabbit HM13 (74% identical), tropical clawed frog hm13 (67% identical), zebrafish hm13 (67% identical), Drosophila melanogaster Spp (52% identical), Caenorhabditis elegans imp-2 (36% identical). Paralogues in human: SPPL2B (26% identical), SPPL2A (22% identical), SPPL2C (22% identical), SPPL3 (18% identical).
Diseases named in the same sentence as HM13 in open-access papers:
HM13 is named in the same sentence as 58 diseases in open-access papers, as found by Europe PMC text mining. Sharing a sentence is not in itself a finding about the gene and the disease. The quoted sentences say what the papers report.
breast carcinoma (9 papers, 2018 to 2025). "In the present study, we performed a series of experiments to elucidate the function and underlying molecular mechanism of HM13 in breast cancer." (PMID 36153332, 2022). "CCK-8 assay, together with EdU assay suggested that IGF-1 reversed the inhibition of breast cancer cell proliferation caused by the knockdown of HM13." (PMID 36153332, 2022). "With respect to the mechanism of HM13 deregulation in breast cancer, we demonstrated that aberrant methylation in the neighbourhood of the HM13 promoter was linked to deregulation of its expression." (PMID 30297886, 2018). "Interestingly, in breast cancer, most prominently in the luminal B subtype, overexpression of HM13 was found to be caused by its biallelic expression due to the loss of imprinting, and it was independent of the copy number gain." (PMID 36461044, 2022). "Recent studies have reported that elevated HM13 expression correlates with poor prognosis in lung cancer, hepatocellular carcinoma, breast cancer, and glioblastoma patients." (PMID 40399808, 2025). "Based on TCGA database, we found that the expression of HM13 was significantly aberrant in breast cancer tissues." (PMID 36153332, 2022). "Mechanistically, miR-760 negatively regulated HM13 mRNA expression and made suppressive effects on breast cancer." (PMID 36153332, 2022). "In the present study, HM13 was identified to have an oncogenic function in breast cancer through autophagy triggered by ER-stress." (PMID 36153332, 2022). "Kaplan Meier plot analysis suggested that higher HM13 expression level was correlated with worse prognosis of breast cancer patients." (PMID 36153332, 2022). "Functional investigations indicated that HM13 exerted its oncogenic role by promoting the proliferation and metastasis of breast cancer cells." (PMID 36153332, 2022). "In summary, our work confirmed that HM13 was highly expressed in breast cancer, at least in part, by facilitating the degradation of autophagosomes." (PMID 36153332, 2022). "The underlying mechanism between miRNA dysregulation and the rationale of aberrant HM13 expression in breast cancer was further investigated." (PMID 36153332, 2022). "Highly expressed HM13 in breast cancer was related to a late T grade and a poor histological type of breast cancer." (PMID 36153332, 2022). "In the present study, we uncovered that HM13 was highly expressed in breast cancer and correlated with worse prognosis." (PMID 36153332, 2022). "The abnormally high expression of HM13 motivated us to explore why it was upregulated in breast cancer." (PMID 36153332, 2022). "Obviously, the accumulated evidence highlights the potential of HM13 as a novel therapeutic target for breast cancer treatment." (PMID 36153332, 2022). "After the analysis in TCGA together with the validation in cell lines and tumor tissues, we found the abnormally high expression level of HM13 in breast cancer." (PMID 36153332, 2022). "We then verified that HM13 was a direct target of miR-760 functioned as a tumor -suppressor in breast cancer." (PMID 36153332, 2022). "Four algorithms (TargetScan, mirWalk, mirRDB, and miTarBase) were used to screen and predict the putative miRNAs targeting HM13 gene in breast cancer." (PMID 36153332, 2022). "Further research is, therefore, necessary to unravel the exact mechanism(s) and consequences of (de)regulation of HM13 in breast cancer." (PMID 30297886, 2018). "This new miR-760/HM13 axis enhanced our understanding of breast cancer progression." (PMID 36153332, 2022). "We performed rescue experiments to detect whether miR-760 functionally targeted HM13 in breast cancer." (PMID 36153332, 2022). "According to the growth curves derived from the CCK-8 assay, knockdown of HM13 could slow down the growth rate of breast cancer cells, in line with the results of the colony formation and EdU assays." (PMID 36153332, 2022).
breast carcinoma (continued). "To detect whether HM13 promotes breast cancer progression through autophagy, we conducted a series of functional experiments." (PMID 36153332, 2022). "Taken together, these findings elucidated that HM13, targeted by miR-760, could play an oncogenic role in breast cancer by inducing autophagic inhibition and facilitating PI3K-AKT-mTOR pathway." (PMID 36153332, 2022). "In addition, IHC staining derived from breast cancer tissues of tumor subcutaneous mice model demonstrated that the positive rates of HM13 and Ki-67 were reduced in the HM13 knockdown group, compared to that of the control group." (PMID 36153332, 2022). "Wound healing assays, as well as transwell assays elucidated that downregulated HM13 could suppress the migration and invasion abilities of breast cancer, while HM13 overexpression could facilitate breast cancer metastasis." (PMID 36153332, 2022). "Moreover, miR-760 expression was inversely correlated with HM13 expression in 30 pairs of breast cancer tissues." (PMID 36153332, 2022). "Moreover, our characterization of this new miR-760/HM13 axis enhanced our understanding of breast cancer progression." (PMID 36153332, 2022). "The findings suggested HM13 could act as a novel therapeutic target candidate for breast cancer and supported the idea that autophagy inducers might represent a new approach to breast cancer." (PMID 36153332, 2022). "Moreover, research has shown that LOI and upregulation for the HM13 gene have both been involved with breast cancer, in addition to its functional relationship with glioblastoma progression." (PMID 34906185, 2021). "The results showed that downregulated HM13 could suppress the breast cancer proliferation in vivo." (PMID 36153332, 2022). "Therefore, miR-760 could mediate autophagy and PI3K-AKT- mTOR pathway by targeting HM13 in breast cancer." (PMID 36153332, 2022). "It indicated the knockdown of HM13 could trigger autophagic synthesis in breast cancer cells." (PMID 36153332, 2022). "Our findings suggested HM13 could act as a novel therapeutic target candidate for breast cancer and supported the idea that autophagy inducers might represent a new approach to treat breast cancer." (PMID 36153332, 2022). "Downregulation of HM13 could suppress breast cancer cell proliferation and metastasis abilities." (PMID 36153332, 2022). "Taken together, HM13 could accelerate breast cancer progression." (PMID 36153332, 2022). "For example, miR-760 targets the HM13 gene which performs oncogenic function by activating the PI3K/AKT/mTOR pathway and promoting cell proliferation in breast cancer." (PMID 40142329, 2025).
lung carcinoma (9 papers, 2015 to 2025). "In this study, aiming to develop a lung cancer-specific diagnostic model with improved accuracy, we expanded the imprinted gene panel with a fourth imprinted gene minor histocompatibility antigen H13 (HM13)." (PMID 34906185, 2021). "As amplification of HM13 locus has been previously reported in several lung cancer cell lines, it is very likely to demonstrate multiallelic expressions using our QCIGISH method." (PMID 34906185, 2021). "A recent study identified aberrant allelic expression of both GNAS and HM13 at 20q11-13.32, as well as that of imprinted GRB10 at 7p12.1 and SNRPN 15q11.2 as useful biomarkers for lung cancer diagnosis." (PMID 36461044, 2022).
hepatocellular carcinoma (5 papers, 2009 to 2026). A malignant tumor that arises from hepatocytes. "Additionally, by transcriptomics and proteomics, we verified the expression and prognostic value of HM13 in hepatocellular carcinoma (HCC)." (PMID 36046831, 2022).
viral infection (5 papers, 2020 to 2024). "Cleavage of transmembrane segments on target proteins by the aspartyl intramembrane protease signal peptide peptidase (SPP, encoded by HM13) has been linked to immunity, viral infection and protein quality control." (PMID 39513424, 2024).
colorectal cancer (2 papers, 2018 to 2025). A primary or metastatic malignant neoplasm that affects the colon or rectum. "Importantly, deregulation of HM13—located on 20q—has been revealed in colorectal carcinoma: the often observed 20q gain in this tumour is associated with higher HM13 expression, which was demonstrated to lead to accelerated growth of the tumour." (PMID 30297886, 2018). "Further investigation of HM13 protein function and related signaling pathways should help to determine whether HM13 can be used as a potential biomarker to predict 5-FU chemotherapy resistance in colorectal cancer." (PMID 40399808, 2025).
renal carcinoma (2 papers, 2024 to 2026). A carcinoma arising from the epithelium of the renal parenchyma or the renal pelvis. "In summary, here we demonstrated clear LOI of HM13 in renal cancer causing HM13 overexpression, which leads to poor prognosis." (PMID 39199324, 2024).
atherosclerosis (1 paper, 2025). A disease characterized by the build-up of fatty material and calcium deposition in the arterial wall resulting in partial or complete occlusion of the arterial lumen. "We demonstrated that HM13/SPP downregulates cholesterol efflux transporter expression and enhances foamy macrophage formation and atherosclerosis via promoting ERAD‐mediated HO‐1 proteasomal degradation." (PMID 40112173, 2025). "A weighted gene co‐expression network analysis on the Stockholm Atherosclerosis Gene Expression (STAGE) patient cohort identifies AIP as a negative correlate of Histocompatibility Minor 13 (HM13), which encodes the ER‐associated degradation (ERAD) protein Signal Peptide Peptidase (HM13/SPP)." (PMID 40112173, 2025). "Mechanistically, HM13/SPP enhances foamy macrophage formation and atherosclerosis via promoting ERAD‐mediated proteasomal degradation of the metabolic regulator Heme Oxygenase‐1 (HO‐1)." (PMID 40112173, 2025).
dengue (1 paper, 2018). "Of these interesting hits, HM13 or signal peptide peptidase is involved in processing of signalling peptides after ER membrane translocation, a pathway that has been reported to be critical for several flaviviruses including dengue." (PMID 29451494, 2018).
glioma (1 paper, 2022). A benign or malignant brain and spinal cord tumor that arises from glial cells (astrocytes, oligodendrocytes, ependymal cells). "Knocking out HM13 significantly inhibits tumor cell survival, reduces cytokine secretion in EGFRvIII glioma cells, and affects the biological behavior of surrounding cells by mediating the TGF-β pathway." (PMID 36046831, 2022).
intrauterine growth restriction (1 paper, 2022). "HM13 is essential for fetal development and is related to placental stress in pregnancy, and intrauterine growth restriction." (PMID 35501310, 2022).
polydactyly (1 paper, 2024). A disease characterized by the presence of polydactyly, including syndromic and non-syndromic forms. "Furthermore, three genes affecting the development of polydactyly, angiopoietin 4 (ANGPT4), histocompatibility minor 13 (Hm13), and solute carrier family 52 member 3 (SLC52A3), were identified by overlap analysis." (PMID 38612286, 2024).
cancer (22 papers, 2006 to 2026). A tumor composed of atypical neoplastic, often pleomorphic cells that invade other tissues. "HM13 expression has already been associated with prognosis in pan-cancer analysis, among which ccRCC is included." (PMID 39199324, 2024). "Growing evidence supports the association between HM13 expression, tumor-infiltrating immune cells (TIICs), and cancer." (PMID 35964022, 2022). "Hence, these results suggest that HM13 LOI is relevant in cancer and may have multiple causes, including copy number gains and aberrant imprinting." (PMID 39199324, 2024). "We discovered that HM13 expression was remarkably upregulated in most cancer types by TCGA database and GTEx database analyzing with the SangerBox 3.0 web software." (PMID 40399808, 2025). "By analyzing scRNA-seq data from 486 cancer cells across subtypes, we identified multiple SNPs in imprinted genes, including HM13, MEST (PEG1), SNHG14 and PEG10, showing consistent biallelic expression." (PMID 39766305, 2024). "On the other hand, HM13 is located on chromosome 20q, known to be commonly gained in cancer, and also leading to HM13 expression upregulation in stage 1 ccRCC." (PMID 39199324, 2024). "Combined, these results argue for more in-depth functional pan-cancer analyses of HM13—a signal peptide peptidase involved in epitope generation—and the causes and impact of its deregulation in cancer." (PMID 39199324, 2024). "Herein, the pan-cancer expression of HM13 in tissues was described using multi-omics data, thus providing a new dimension for understanding the occurrence of tumors." (PMID 36046831, 2022). "Histocompatibility minor 13 (HM13) is a signal sequence stubbed intramembrane cleavage catalytic protein that is essential for cell signaling, intracellular communication, and cancer." (PMID 35964022, 2022). "The prognostic significance of abnormal HM13 pan-cancer expression was evaluated by univariate Cox regression and Kaplan-Meier analyses." (PMID 36046831, 2022). "Expression of HM13 correlated strongly with pan-cancer immune checkpoint gene expression and immune cell infiltration." (PMID 36046831, 2022). "In conclusion, we delineated the pan-carcinoma expression profile of HM13 and found that its abnormally upregulated expression correlated with poor prognosis in patients with tumors." (PMID 36046831, 2022). "For example, in cancer, GNAS, BCR and SNRPN showed both expression downregulation and CNV losses, while for HM13, gains were linked with overexpression." (PMID 30297886, 2018). "HM13 is the only gene in which both DI and higher expression in cancer was identified, indicating LOI." (PMID 30297886, 2018). "Therefore, our findings demonstrate that HM13 is a potential pan-cancer prognostic marker, thus providing a new dimension for understanding tumor development." (PMID 36046831, 2022). "The sole example where DI could be attributed to LOI was HM13, which exhibited overexpression in cancer, particularly in LumB tumours, due to re-expression of the normally silenced allele." (PMID 30297886, 2018). "Given that HM13 is located on the 20q locus, often gained in cancer, we also evaluated whether CNV gains may explain DI, but DI appeared independent from CNV for all imprinted HM13 SNPs." (PMID 30297886, 2018). "This may be particularly relevant for HM13, given that HM13 is expressed in blood and that admixture of biallelically expressed HM13 could theoretically lead to both higher HM13 expression and LOI in cancer." (PMID 30297886, 2018).